S100B (S100 calcium binding protein B)
Diseases named in the same sentence as S100B in open-access papers (continued):
Sharing a sentence is not in itself a finding about the gene and the disease.
chronic kidney disease (4 papers, 2018 to 2024). Impairment of the renal function secondary to chronic kidney damage persisting for three or more months. "Interestingly, transiently elevated levels of S100B are suggestive of minor acute cerebral damage in the first days following MI and are associated with depressive symptoms in the year following MI and in patients with end-stage renal disease." (PMID 39201780, 2024). "It was noted that the median S100B concentration in serum after dialysis (17.4 μg) is significantly higher than before dialysis (5 μg) in patients with chronic kidney disease." (PMID 39519343, 2024). "It is also known that S100B levels in patients with end-stage renal disease increase with a decrease in glomerular filtration rate, and S100B levels depend on the timing of blood collection in relation to dialysis." (PMID 39519343, 2024). "This can be attributed to a potential dysregulation of neuroplasticity in patients with T2DM compared to other populations, such as patients with End Stage Renal Disease, where the elevation of S100B serum levels could be the result of the accumulation of uremic toxins." (PMID 30581620, 2018). "Secondly, depressive patients with End Stage Renal Disease (ESRD) have increased S100B serum levels compared to nondepressives." (PMID 30581620, 2018).
demyelinating disease (4 papers, 2014 to 2025). A broad group of disorders that affect the myelin sheaths that cover the neurons. "Future studies should further investigate the mechanistic relationship between S100B, neurofilament stability, and microglial-mediated remyelination to explore its therapeutic potential in MS and other demyelinating disorders." (PMID 40227512, 2025). "It has been described a high release of S100B in demyelinating disorders, and we have previously shown that in MS post-mortem active lesions, there is an elevated expression of S100B by astrocytes and of its receptor RAGE by macrophages/microglial cells." (PMID 33100970, 2020).
diabetic neuropathy (4 papers, 2021 to 2025). A chronic, pathological complication associated with diabetes mellitus, where nerve damages are incurred due to diabetic microvascular injury involving small blood vessels that supply these nerves, resulting in peripheral and/or autonomic nerve dysfunction. "Another substantial mechanism apparently present at the stage of pre-diabetic neuropathy is the stimulation of inflammatory processes in the sciatic nerve, reflected by the elevated expression of the calcium binding protein, S100B in the neural tissue upon HFD feeding to mice." (PMID 34833143, 2021). "When separately analyzed to detect subgroup differences based on type of peripheral neuropathy, diabetic neuropathy had increased NFL (SMD, 0.77 [95% CI, 0.42 to 1.13]; P < .001; I2 = 0%) and S100B (SMD, 0.93 [95% CI, 0.60 to 1.25]; P < .001; I2 = 99%)." (PMID 36574244, 2022). "We hence confirmed that the PMSCs transplant significantly augmented the expression of S100β, indicating that PMSC treatment of diabetic neuropathy might be related to Schwann cells." (PMID 36440182, 2022).
experimental autoimmune encephalomyelitis (4 papers, 2012 to 2025). An autoimmune demyelinating disease of the central nervous system that is produced experimentally in animals by the injection of homogenized brain or spinal cord in Freund's adjuvant. "The calcium-binding protein S100B is elevated in MS patients, and its targeting has shown promise in reducing disease severity in experimental autoimmune encephalomyelitis (EAE) models." (PMID 40227512, 2025). "Experimental autoimmune encephalomyelitis, using an injection of S100B (a glial cytosolic protein involved in astrocyte proliferation, neuron survival, and neurite outgrowth in the brain), can induce inflammatory lesions of the cerebral white matter accompanied by panuveitis and retinitis." (PMID 23213530, 2012).
leukoaraiosis (4 papers, 2017 to 2022). "S100B (calcium binding protein B), the S100B/asymmetric dimethylarginine ratio, and the homocysteine level correlated with baseline small vessel disease burden as leukoaraiosis, lacunar infarct, and deep microbleeds." (PMID 34356837, 2021).
liver diseases (4 papers, 2013 to 2023). "Regarding liver diseases, there have been a few studies reporting serum S100B as a neuromarker of HE in patients with fulminant hepatitis." (PMID 36766438, 2023). "In the future, basic and clinical studies are necessary to identify the effect of liver dysfunction on serum S100B levels in various liver diseases." (PMID 36766438, 2023). "The potential of specific isoforms of S100 proteins as circulating biomarkers, i.e., S100A4, S100A8, S100A9, S100A12 or S100B, has already been outlined for non-hepatic diseases such as rheumatic diseases and leukemia, respectively." (PMID 36232334, 2022). "Therefore, in liver disease, subsequent research on the clinical value of S100B should include a normal control group and be designed considering the source of variation affecting the levels of serum S100B concentrations." (PMID 36766438, 2023). "Additionally, ammonia is known to be related to the pathogenesis of liver-related complications, including liver cell damage, immune dysfunction, sarcopenia, and portal hypertension; thus, together with S100B, ammonia may be an interesting indicator of LC." (PMID 36766438, 2023). "In addition to S100B increased expression in activated astrocytes, observed in neurological diseases, astrocyte-derived S100B expression were also reported to significantly increase in systemic diseases such as mild to severe liver diseases." (PMID 26959008, 2016).
obstructive sleep apnea syndrome (4 papers, 2013 to 2025). Cessation of air flow during sleep due to upper airway obstruction. "Elevated S100B plasma levels but not NSE levels have been reported for individuals affected by an obstructive sleep apnea syndrome." (PMID 39495288, 2025).
prion disease (4 papers, 2020 to 2026). A transmissible disease that is caused by a protein that is able to induce abnormal folding of normal cellular proteins, leading to characteristic spongiform brain changes, which are associated with neuronal loss without an inflammatory response. "This interaction provides a biologically plausible explanation for the diagnostic value of S100B in certain genetic and atypical prion disease subtypes, especially in cases where classical prion-specific assays such as RT-QuIC are negative." (PMID 41516424, 2026). "The 14-3-3, S100B, and total tau proteins are biomarkers that can help assess the probability of prion disease." (PMID 39687838, 2025). "Measurement of CSF NSE and S100B has respective sensitivity values of 79%–85% and 65%–94% for sCJD, 0%–64% and 20%–87% for genetic prion diseases (gCJD, GSS, and FFI), and 52% and 78% for vCJD, while specificity values are 83–92% for NSE and 76%–90% for S100B." (PMID 33195151, 2020).
psoriasis (4 papers, 2021 to 2023). An autoimmune condition characterized by red, well-delineated plaques with silvery scales that are usually on the extensor surfaces and scalp. "S100A4 and S100B have also been implicated in the pathogenesis of psoriasis." (PMID 35892571, 2022). "S100B is expressed in dendritic cells and cells with a neurogenic origin, and increased levels of this protein have been reported in neurological diseases, psoriasis, and other inflammatory disorders." (PMID 34207181, 2021). "However, the detailed mechanism of action of S100B in psoriasis remains unknown." (PMID 37891988, 2023). "Members of the S100 family of proteins intensively studied in the course of psoriasis include S100A4 (Figure A1), S100A7 (Figure A2), S100A8 (Figure A3), S100A9 (Figure A4), S100A12 (Figure A5), S100B (Figure A6) and S100A15, indicating their involvement in the pathogenesis of the disease." (PMID 36235175, 2022). "Notably, S100B is highly expressed in the skin of patients with non-lesional psoriasis versus psoriatic lesions." (PMID 37891988, 2023).
retinal degeneration (4 papers, 2020 to 2023). Degeneration of the retina. "In particular, S100β may prove to be a target for suppressing chronic gliosis in retinal degeneration." (PMID 37298126, 2023). "Here, the intensity remained unchanged in comparison to the control group, confirming a recent study result - that 14 days after immunization might be too early in the retinal degeneration process of systemically immunized S100B animals." (PMID 35053014, 2021). "As gliosis involves macroglia, we investigated their gliotic response to determine the role of S100β and intermediate filaments (IFs) GFAP, vimentin, and nestin during tissue repair in a laser-induced model of retinal degeneration." (PMID 37298126, 2023). "In order to investigate if the data from the mouse model correspond to the characteristics of retinal degeneration in patients, three human retina samples containing drusen and three samples without drusen were stained with the selected gliotic markers (vimentin, nestin, GFAP, and S100β)." (PMID 37298126, 2023).
Shock (4 papers, 2015 to 2023). The state in which profound and widespread reduction of effective tissue perfusion leads first to reversible, and then if prolonged, to irreversible cellular injury. "Furthermore, other markers of cerebral cellular damage have also been described following haemorrhagic shock in other studies, such as an increased level of glycerol in brain tissue and increased plasma levels of S100B, findings which support the presently reported results." (PMID 25888229, 2015).
viral meningitis (4 papers, 2019 to 2025). Inflammation of the membranes surrounding the brain and spinal cord due to a viral infection. "CSF levels of HBP and NGAL, as well as the blood level of S100B, could help discriminate between bacterial and viral meningitis before considering antibiotic treatment." (PMID 35740230, 2022).
virus infection (4 papers, 2017 to 2026). "To validate the viral infection status of ORF3a-positive and control brain tissues, we examined the presence of the viral nucleocapsid (NCp) protein by co-immunostaining with S100B, an astrocytic marker of gray matter." (PMID 40802282, 2025). "We then expressed these Myc-DDK-tagged mut and wt S100B in neuronal cultures by Lenti-virus infection to analyze effects on cellular zinc pools, using uninfected cells as control." (PMID 29386995, 2017).
Allergy (3 papers, 2010 to 2023). An allergy is an immune response or reaction to substances that are usually not harmful. "The IL-16/IL-10 ratios reflected sensitivity to allergy and were associated with S100B levels and oppositional symptoms." (PMID 20509936, 2010). "Third, while across all children the sensitivity to allergy reflected increased levels of IL-16 and IL-10, the latter showed a significant inverse relationship to measures of S100B in the ADHD group." (PMID 20509936, 2010). "Interestingly, top-listed differentially expressed Th17-associated genes S100B, MILR1 and CHI3L1 have been reported to play roles in allergy and asthma." (PMID 24991220, 2014). "c) Decreasing S100B levels in ADHD groups related to decreasing levels of IL-16, but increasing levels IL-10 (independent of age), - where IL-16 and IL-10 correlated with allergy sensitivity." (PMID 20509936, 2010).
amnesia (3 papers, 2012 to 2021). Pathologic partial or complete loss of the ability to recall past experiences ( AMNESIA, RETROGRADE) or to form new memories ( AMNESIA, ANTEROGRADE). "Consecutive adult patients with mild TBI (GCS 14-15, loss of consciousness and/or amnesia), managed with the aid of S100B, were prospectively included in this study." (PMID 27765016, 2016). "Adult ([≥]18 years) patients with MHI (GCS 14–15, loss of consciousness and/or amnesia and no additional risk factors) and S100B sampling within 3 hours were prospectively included in this validation study." (PMID 23102492, 2012).
aneurysm (3 papers, 2010 to 2023). Bulging or ballooning in an area of an artery secondary to arterial wall weakening. "The results of univariate analysis revealed that the patients with good and poor prognosis had significantly different age, aneurysm diameter, Hunt-Hess grade, timing of surgical treatment and levels of S100B, MCP-1 and CRP (P<0.05)." (PMID 38357151, 2023). "In addition to the widely studied NSE and S100β, 6 additional neuron-enriched proteins that are released from degenerating neurons increase within a week of aneurysm rupture." (PMID 22174930, 2011).
aseptic meningitis (3 papers, 2019 to 2023). Inflammation of the membranes surrounding the brain and spinal cord without a bacterial pathogen. "Simultaneously, S100B levels were higher in the TBM and BM groups than in the control and aseptic meningitis groups (P < .05)." (PMID 38115295, 2023).
aspergillosis (3 papers, 2011 to 2016). Aspergillosis is an infection, growth, or allergic response caused by the Aspergillus fungus. "These in vivo findings confirm that the spatiotemporal integration of signals from TLRs and RAGE by S100B limits pathogen– and danger–induced inflammation in murine aspergillosis." (PMID 21423669, 2011). "To determine the role of the S100B/RAGE axis in response to the fungus, we evaluated parameters of infection, inflammation and adaptive immunity in RAGE KO mice with pulmonary aspergillosis." (PMID 21423669, 2011). "This occurred through epithelial cell–released S100B that paracrinally inhibited the TLR2–dependent activity of recruited PMNs, a finding consistent with the ability of RAGE to impair neutrophil functions as well as with the down–regulated TLR2 activity in pulmonary aspergillosis." (PMID 21423669, 2011).
asphyxia (3 papers, 2015 to 2022). A state of general hypoxia and hypercapnia (abnormally elevated carbon dioxide (CO2) levels in the blood), resulting in acidosis, which affects all tissues in the body. "In the present study, a statistically significant increase was found in the S100B concentration of calves with perinatal asphyxia compared to healthy calves at the time of admission, 24, 48, and 72 h." (PMID 36428450, 2022). "Moreover, S100B was suggested to be a potential marker for the early detection of IVH in infants with perinatal asphyxia before clinical examination and transtemporal ultrasound display pathological changes." (PMID 36430274, 2022). "AB42 and S100B are significantly changed in neonatal pigs subjected to hypoxia compared to controls and thus may be valuable biomarkers of perinatal asphyxia." (PMID 26501201, 2015).
asthma (3 papers, 2014 to 2023). "Our findings related to the influence of asthma on the relationship between brain microstructure and CSF concentrations of S100B and IL-6 suggest a complex immune profile in those with asthma." (PMID 37377978, 2023). "Higher concentrations of the pleiotropic cytokine IL-6 and the glial marker S100B were associated with more salubrious white matter metrics in asthma, but not in controls." (PMID 37377978, 2023). "Similarly, in asthma but not controls, higher concentrations of the glial marker S100B were associated with lower FISO, MD, RD, and AD in the corpus callosum and parts of the corona radiata." (PMID 37377978, 2023). "There were unexpected relationships between IL-6 and S100B and white matter microstructure in those with asthma, but not controls." (PMID 37377978, 2023). "Although levels of RAGE ligands S100B, S100A8/A9, S100A1, S100A6, AGEs may have a biomarker role in cardiovascular disease, in asthma, there are scarce data advocating such a role." (PMID 37371535, 2023).
autoimmune disease (3 papers, 2015 to 2025). A disorder resulting from loss of function or tissue destruction of an organ or multiple organs, arising from humoral or cellular immune responses of the individual to their own tissue constituents. "S100B depletion also reduced levels of MHC-II, an antigen presenting molecule often related to autoimmune diseases and that also triggers inflammatory cascades." (PMID 40227512, 2025).
Autoimmunity (3 papers, 2011 to 2023). The occurrence of an immune reaction against the organism's own cells or tissues. "Local S100B over-expression is associated with enhanced inflammation in the human gut, thus playing a major role in gut–brain-induced inflammation and autoimmunity." (PMID 37509576, 2023). "This may also predict an inherent risk of autoimmunity associated with S100B." (PMID 21423669, 2011). "In this study, we aimed to investigate the relationship between serum levels of S100B protein, a marker of neuronal damage, and antiribosomal P protein antibodies as indicators of the presence of autoimmunity in a group of autistic children." (PMID 22420334, 2012).
central obesity (3 papers, 2020 to 2023). "Moreover, serum levels of S100B were positively correlated with abdominal obesity and triglyceride serum levels." (PMID 37960185, 2023).
colon adenocarcinoma (3 papers, 2019 to 2022). "One research group has reported finding that the RAGE ligand, S100B, induces the hallmarks of cancer cachexia associated with experimental colon adenocarcinoma or Lewis lung carcinoma." (PMID 36497194, 2022). "Given this background, the present research aimed at evaluating the putative effects of S100B protein on cancer cells proliferation, invasion, migration and on the release of pro-angiogenic mediators in human colon adenocarcinoma Caco-2 cell line." (PMID 31266264, 2019).
dementia with Lewy bodies (3 papers, 2014 to 2024). "CSF S100B most favorably discriminated patients with PD and dementia with Lewy bodies (DLB) (n = 45) from controls (n = 20)." (PMID 35448530, 2022).
dyslexia (3 papers, 2010 to 2023). A learning disorder characterized by an impairment in processing written words. "The recent identification of S100B as a novel dyslexia candidate gene along with three other genes (i.e., PCNT, DIP2A, and PRMT2) mapping to chromosome region 21q22.3 suggests that decreases in S100B expression might contribute to certain dyslexia phenotypes." (PMID 20827421, 2010).
fracture (3 papers, 2009 to 2022). "In patients suffering tubular bone fractures in addition to TBI (n = 21, all GCS 14-15), mean prehospital and in-hospital S100B concentrations were 0.73 μg/l (95%CI 0.47; 1.14) and 0.39 μg/l (95%CI 0.26; 0.58) respectively." (PMID 35469266, 2022).
Fulminant hepatic failure (3 papers, 2023 to 2024). Hepatic failure refers to the inability of the liver to perform its normal synthetic and metabolic functions, which can result in coagulopathy and alteration in the mental status of a previously healthy individual. "Several studies have suggested that elevated serum S100B levels may be a diagnostic marker of overt HE in fulminant hepatic failure or cirrhosis." (PMID 36766438, 2023). "Elevated S100B has also been shown in patients with fulminant hepatic failure." (PMID 36983411, 2023). "However, based on the results of the present study, the elevated serum S100B levels observed in fulminant hepatic failure may be the result of not only astrocyte injury but also liver damage itself." (PMID 36766438, 2023).
Headache (3 papers, 2024 to 2026). Cephalgia, or pain sensed in various parts of the head, not confined to the area of distribution of any nerve. "Still, S100-B was positively correlated to individuals who continued to play after suffering a head injury accompanied with subsequent headache in at least 50% of the cases." (PMID 38419110, 2024).